FOXC1 (forkhead box C1)
Diseases named in the same sentence as FOXC1 in open-access papers (continued):
Sharing a sentence is not in itself a finding about the gene and the disease.
cancer (continued). "Previous studies have indicated that FoxC1 is overexpressed in human cancer and acts as an oncogene to promote proliferation and metastasis." (PMID 32373221, 2020). "Another transcription factor involved in cancer progression is FOXC1 (Forkhead box C1), a key regulator of diverse cellular functions." (PMID 32722129, 2020). "Like most developmental transcription factors, FOXC1 is subject to multiple layers of regulation, providing a diversity of opportunities for deregulation in cancer." (PMID 30764547, 2019). "Clinical studies have also found that the increased expression of FOXC1 is closely related to a poor prognosis in many cancer operations." (PMID 31623173, 2019). "Collectively, these data strongly indicate that FOXC1 enhances cell proliferation and alters cell fate across diverse cancer types." (PMID 30764547, 2019). "Overall, despite clear indications of potential post-translational deregulation of FOXC1 in cancer, the potential mechanisms at play remain very poorly understood." (PMID 30764547, 2019). "Using DNA-binding assays, the authors posited that FOXC1 enhances cancer stem cell activity by upregulating β-catenin, the transcriptional mediator of WNT signaling." (PMID 30764547, 2019). "Of particular interests to this study, overexpression of FOXC1 in A549 cells significantly promoted cancer cell growth and invasion." (PMID 31783879, 2019). "For example, overexpression of FOXC1 (forkhead box C1), a member of the forkhead box of transcription factors, has been observed in several cancers." (PMID 30866526, 2019). "Taken together, these data indicated that miR-138-5p directly targeted FOXC1 to reduce cancer cell growth and invasion." (PMID 31783879, 2019). "This review explores current evidence for FOXC1 deregulation in cancer and the putative mechanisms by which FOXC1 confers its oncogenic effects." (PMID 30764547, 2019). "Given that FOXC1 contributes to a physiologic EMT during embryonic neural tube formation, it is perhaps unsurprising that FOXC1 is also implicated with the EMT in cancer." (PMID 30764547, 2019). "We found Forkhead box C1 (FOXC1), which is one of the transcription factors for miR-31-5 and also related to cancer cell proliferation." (PMID 31623173, 2019). "The current views on its function and molecular mechanisms reveal that FOXC1 as an oncogene plays multiple roles in cancer progression and metastasis by affecting different targets." (PMID 29357938, 2018). "FOXC1's role in inducing the EMT process to increase cancer cell migration and invasion offers a possible explanation for how overexpressed FOXC1 mRNA was found to elevate HCC metastatic potential in vitro and encourage lung cell metastasis in vivo." (PMID 29487724, 2018). "The authors found that FOXC1 expression was significantly higher in the late T-stage (T3-T4) of the cancer than that in the early T-stage (T1-T2) of the cancer (p-value = 0.023)." (PMID 30564302, 2018). "Within this paper we will review FOXC1's impact in cancer, focusing on FOXC1's role in signaling pathways, gene regulation, and interactions with other proteins and how these factors affect the nature of this malignant disease." (PMID 29487724, 2018). "Proliferation and invasion of cancers were increased by FOXC1 by mediating NF-κB, MST1R and KLF4 expression." (PMID 29552326, 2018). "Accordingly, our analysis demonstrated that the expression level of FOXC1 was much higher than the mean expression level of all the genes in cancer cell lines, and we provide molecular genetic evidence that FOXC1 regulates the transcription of CD147." (PMID 29560120, 2018). "The authors found that FOXC1 expression was significantly higher in the late T-stage (T3-T4) of the cancer than that in the early T-stage (T1-T2) of the cancer (p-value = 0.012)." (PMID 30564302, 2018).
cancer (continued). "This review discusses not only the role of FOXC1 in cancer cell progression, proliferation, differentiation, and metastasis, but also the underlying mechanisms of how FOXC1 can contribute to aggressive cancer phenotypes." (PMID 29487724, 2018). "Other studies have demonstrated that FOXC1 regulates cancer stem cell properties through the activation of smoothened-independent Hedgehog signaling." (PMID 29976975, 2018). "Here, we characterized the relationship between FOXC1 and cancer progression by conducting a meta-analysis of studies that reported the frequency of FOXC1 expression in tumors of different stages (T1, T2, T3, T4)." (PMID 30564302, 2018). "In cancer, FOXC1 and FOXC2 are involved mainly in inducing angiogenesis, invasion and metastasis, invading growth suppressors, genome instability and mutation, and sustaining proliferative signaling." (PMID 30360388, 2018). "In summary, recent investigations of FOXC1 are beginning to reveal a key protein at the juxtaposition of critical oncogenetic pathways for many cancers." (PMID 29487724, 2018). "In contrast to how reduced FOXC1 underlies ARS, an increase in function and activity of FOXC1 is responsible for cancer cell proliferation, differentiation, survival and metastasis." (PMID 29487724, 2018). "As a downstream signaling molecule of IGF-1R, FOXC1 has been shown to have the same effect on cancer cells in terms of angiogenesis, proliferation, tumorigenesis, and metastasis." (PMID 29976975, 2018). "In contrast, FOXC1 has been reported to be essential for maintaining stem cell properties in normal and cancer cells as well as the microenvironment." (PMID 29070831, 2017). "FOXC1 was reported as a target of miR-639, as evidenced by EMT in FOXC1 overexpressing cancer cells and the loss of TGFβ-induced EMT in FOXC1-silenced cells." (PMID 28708091, 2017). "FOXC1 promotes cancer progression by regulating the epithelial-mesenchymal transition (EMT), cell proliferation and migration." (PMID 27802187, 2017). "Other studies described that NF-κB regulates cancer stem cell properties, which complements our previous study that FOXC1 also regulates cancer stem cell function through a Hedgehog/Gli-mediated pathway." (PMID 28629477, 2017). "The contradictory results obtained from different cancer cells and primary normal human KC suggest that FOXC1 has pleiotropic functions." (PMID 27907090, 2016). "All in all, these results were similar to findings in previous studies, which further confirmed that FOXC1 promotes development of cancer." (PMID 27533251, 2016). "Dysregulation of the FOXC1 protein contributes to carcinogenesis, including proliferation, apoptosis, differentiation, invasion and metastasis of several human cancers." (PMID 26198045, 2016). "We confirm here a very recent report on the presence and extent of DNA methylation in the promoter of FOXC1, a member of the forkhead protein family, many members of which are involved in the development and progression of cancer." (PMID 20338046, 2010). "Furthermore, immunohistochemical staining of collected carcinoma and paraneoplastic tissues exhibited a notable increase in FOXC1 expression in ESCC." (PMID 38413558, 2024). "In recurrent cancers, FOXC1 production is correlated with reduced or extremely traced estrogen receptor (ER) expression, and through inhibiting GATA binding protein 3 binding, FOXC1 participates in ER silencing and has been linked to endocrine resistance." (PMID 37626655, 2023). "FOXC1 is known to play an important role in various cancer types." (PMID 38107056, 2023). "Foxc1 was a transcription factor that played important roles in apoptosis, cell proliferation, cellular migration, and cancer progression." (PMID 37626284, 2023). "As for pathological changes, FOXC1 is up-regulated in many carcinomas." (PMID 37445678, 2023).
cancer (continued). "In addition, FOXC1 has a role in the maintenance of hematopoietic stem and progenitor cells in bone marrow and promotes cell proliferation and invasion in human cancer." (PMID 35365611, 2022). "FOXC1 is a transcription factor known to contribute to cancer progression." (PMID 35406487, 2022). "FOXC1 is a transcription factor known to play important roles in cancer progression." (PMID 35406487, 2022). "FOXC1 plays an important role in mediating normal as well as cancer stem cell traits." (PMID 34540690, 2021). "Clinical evidence supporting the role of FOXC1 in cancer progression and metastasis." (PMID 34540690, 2021). "As such, efficacy of Glasdegib in AML and/or other relevant cancers may be predicted by FOXC1 expression status." (PMID 34540690, 2021). "In recent years, several excellent review articles on the role of the Forkhead box C1 (FOXC1) Transcription Factor (TF) in cancer have been published, highlighting the increasing recognition of its importance as a clinically useful biomarker and potential therapeutic target." (PMID 34540690, 2021). "Thus, additional investigations are needed before we are able to draw any conclusions regarding the prognostic utility of FOXC1 expression in these cancers." (PMID 34540690, 2021). "While Bortezomib is required to be administered intravenously (IV), Ixazomib is an oral drug with a superior toxicity profile, making it an ideal candidate for evaluating therapeutic efficacy against FOXC1+ pro-metastatic cancers by targeting the NFĸB signaling pathway via proteasome inhibition." (PMID 34540690, 2021). "Indeed, an excellent and comprehensive systematic review and meta-analysis on the prognostic role of FOXC1 in cancer concluded that FOXC1 expression in cancer is indicative of poor survival outcome." (PMID 34540690, 2021). "The NFĸB signaling pathway and FOXC1 can in certain contexts reinforce one another’s actions indefinitely, thereby constituting a self-perpetuating positive feedback loop that contributes to the maintenance of cancer stem cell traits." (PMID 34540690, 2021). "In this review, we present our viewpoints on the master regulatory role that FOXC1 plays in mediating cancer stem cell traits that include cellular plasticity, partial EMT, treatment resistance, cancer invasion and cancer migration during cancer progression and metastasis." (PMID 34540690, 2021). "Finally, E2F4, FOXC1 and KDM2B play oncogenic roles in other types of cancer as well, supporting their identified pathogenic potential in HL." (PMID 34807923, 2021). "A lncRNA transcribed from the upstream region of the FOXC1 promoter, named FOXCUT (FOXC1 Upstream Transcript), associates with its adjacent mRNAs in “lncRNA–mRNA pairs” and takes part in the regulatory network driving cancer progression." (PMID 32722129, 2020). "Indeed, both of these putative FOXC1 targets are proto-oncogenes which contribute to cell cycle progression and are commonly deregulated in cancer." (PMID 30764547, 2019). "In addition to transcriptional mechanisms regulating the abundance of FOXC1 in cancer cells, a number of studies have highlighted post-transcriptional pathways involving microRNAs (miRNAs) or long non-coding RNAs (lncRNAs)." (PMID 30764547, 2019). "More detailed investigation of this process is now needed to explore whether this is a more generalized process of FOXC1 deregulation in the EMT of other cancers." (PMID 30764547, 2019). "However, other studies have identified additional FOXC1 targets which promote invasion in cancer, including members of the matrix metalloprotease family." (PMID 30764547, 2019). "In addition to being inversely correlated with certain miRNAs, FOXC1 expression is often correlated with that of a neighboring lncRNA called FOXCUT in cancer." (PMID 30764547, 2019). "However, with the notable exception of cyclin D1, the specific downstream targets of FOXC1 which sustain aberrant proliferation in cancer remain largely unidentified." (PMID 30764547, 2019).
cancer (continued). "In this section, the current evidence relating FOXC1 to the hallmarks of cancer will be explored." (PMID 30764547, 2019). "FOXC1 promoted metastasis of cancers by increasing expression of MMP7, NEDD9 and Snail." (PMID 29552326, 2018). "This may be because FOXC1 induces cancer stem cells (CSC)-like properties of the cancer cells via β-catenin." (PMID 30360388, 2018). "In recent years, rapidly accumulating evidence implicates the role of FOXC1 in cancer." (PMID 30564302, 2018). "FOXC2, similar to FOXC1, also has a vital role in the carcinogenesis of various cancers." (PMID 30360388, 2018). "Accumulating evidences have showed that FOXC1 plays critical roles in cancer progression." (PMID 29560120, 2018). "FOXC1 has recently also been shown to have key roles in other cancers as well." (PMID 29487724, 2018). "Additional investigations of FOXC1 are likely to not only illuminate the regulation of key pathways in many different cancers, but may identify novel common entry points for treatments of these cancers." (PMID 29487724, 2018). "Our results suggest that FOXC1 may promote cancer progression by inhibiting the immune response system activation." (PMID 29560120, 2018). "The relationships between FOXC1 and these cancers will be expanded upon later in this review." (PMID 29487724, 2018). "Here we are focusing on roles of FOXC1 and their mechanisms in cancers." (PMID 29552326, 2018). "FOXC1 promoted progress of cancers by activating many signal pathways." (PMID 29552326, 2018). "Besides its role in embryonic development, emerging findings indicate that FOXC1 is also involved in cancer development and progression." (PMID 29070831, 2017). "We have demonstrated that FOXC1 can specifically identify BRCA1-mutant BLBC cancer." (PMID 27708239, 2016). "Other studies have shown that up-regulation of FOXC1 may increase cancer cell invasion and may imply a poor prognosis in cancer patients." (PMID 25875420, 2015). "Furthermore, MMP expressions, as well as some angiogenesis factors such as VEGF-A, have correlated with FOXC1 expression in cancers." (PMID 24889262, 2014). "The FOXC1 gene expression pattern is modified in several human cancer cell lines." (PMID 17134502, 2006). "Furthermore, TGFβ upregulates Foxc1 expression in fibroblasts and cultured eye tissue, in agreement with a previous report that described Foxc1 as a target gene of TGFβ in human cancer-cell lines." (PMID 16403239, 2005). "Moreover, FOXC1 is recognized as a crucial regulator in the advancement of epithelial-mesenchymal transition (EMT), a critical mechanism implicated in the dissemination of cancer and resistance to drugs." (PMID 39093497, 2024). "We also verified the role of transcriptional (TFs proteins) and post-transcriptional (miRNAs) regulators of HubGs in BC through the literature review as follows: The TFs protein FOXC1 is related to key pathways in many cancers and may be a novel treatment for these cancers." (PMID 37893423, 2023). "However, prognostic or functional roles of FOXC1 have yet to be elucidated in these cancers." (PMID 34540690, 2021). "FOXC1, in turn, influences and coordinates multiple biological processes, again utilizing a variety of downstream signaling pathways, by which FOXC1 pro-metastatic cancers participate in the maturation of the aggressive migratory phenotype leading to metastasis." (PMID 34540690, 2021). "This warrants further investigation, since earlier in vitro studies have shown that MAPK-dependent phosphorylation of FOXC1 at S272 directly increases its cellular half-life and transcriptional activity, and thereby might amplify FOXC1-dependent expression of oncogenes in cancer cells." (PMID 30764547, 2019). "Our results indicate that FOXC1 expression is significantly more common in late-stage (T3-T4) tumors than in early stage (T1-T2) tumors and, consequently, that FOXC1 may be a marker for the T-stage of cancer." (PMID 30564302, 2018).
cancer (continued). "In addition, FOXC1 was recently shown to be involved in the development of some cancers." (PMID 27533251, 2016). "Thus, FOXC1 also participated in the development of cancer by regulating the target genes." (PMID 26198045, 2016). "Therefore, we speculated that lncRNA-FOXCUT may regulate the cancer cell growth characteristics of OSCC by regulating FOXC1." (PMID 24889262, 2014). "While FOXC1 and FOXC2 are often upregulated in multiple human cancers to drive EMT and metastasis, their downregulation in late FDIM suggests an alternative mechanism in tumorigenesis." (PMID 40683913, 2025). "Notably, FOXC1 has been implicated in the regulation of stemness, EMT, and immune evasion, while E2F1 is widely known for its involvement in cell cycle activation and DNA replication, serving as a hallmark regulator of proliferative potential in various cancers." (PMID 40496864, 2025). "FOXC1 and JUN assumed critical roles in promoting cancer proliferation, metastasis, and chemoresistance." (PMID 38672263, 2024). "Angiogenesis, invasion, metastasis, invasion of growth eliminators, genomic instability and mutation, and the maintenance of proliferative signals are the primary functions of FOXC1 and FOXC2 in cancer." (PMID 37626655, 2023). "When FOXC1 activates the EMT process in hepatocellular carcinoma, the cancer cells are better able to migrate and invade." (PMID 37626655, 2023). "Functional and mechanistic evidence supporting role of FOXC1 in plasticity, EMT, chemoresistance, cancer progression and metastasis." (PMID 34540690, 2021). "Transcription factor FOXC1 binds to the miR-31 promoter to increase the expression of miR31-5p and regulate LATS2 expression in CRC, resulting in cancer cell resistance to OXA." (PMID 34540690, 2021). "Others have demonstrated the regulation of FOXC1/2, FOXD3, FOXJ1, and FOXN1 expression by β-catenin/TCF in different contexts, but the relevance for cancer biology is less clear in these cases." (PMID 34298659, 2021). "In the same study, FOXC1 enhanced the DNA-binding activity of GLI2, a member of the Hedgehog signaling pathway reported elsewhere as preferentially activated in cancer stem cells." (PMID 30764547, 2019). "By contrast, high miR-31-5p expression regulates the chemoresistance of OXA after FOXC1 binds to the miR-31 promoter of miR-31-5p, which targets LATS2, leading to cancer growth and suppression of apoptosis in OR-LoVo cells." (PMID 31623173, 2019). "However, the role of FOXC1 in cancer metabolism remains unknown." (PMID 30360388, 2018). "Both FOXC1 and FOXC2 have essential roles in the EMT process, angiogenesis, and target cancer stem cells." (PMID 30360388, 2018). "Forkhead box C1 (FOXC1), a member of the FOX protein family, acts as an oncogene in various cancers." (PMID 30189871, 2018). "In hepatocellular carcinoma, FOXC1 triggers the EMT process, which increases the migration and invasion capacities of the cancer cells." (PMID 30360388, 2018). "The elucidation of existing FOXC1-related cancer pathways as well as the investigation into the role of FOXC1 in other cancers may yield not only a strong general prognostic biomarker for belligerent cancer phenotypes, but also precise genetic treatments for individual cases of malignancy." (PMID 29487724, 2018). "Subsequently, other studies have reported that lncRNA BC087858 can be located near forehead box protein C1 (FOXC1), which is a member of the FOX transcription factor family and is important in cancer development." (PMID 27409677, 2016). "Several target genes of miR-204, including HOXA10, MEIS1, FOXC1, MAP1LC3B, BCL2, NTRK2, SOX4 and EphB2, have been identified in different cancers." (PMID 26710269, 2015). "In this study, we first identified a new lncRNA-mRNA pair, FOXC1 and its adjacent lncRNA FOXCUT, as the new form of cancer driver gene compound in OSCC." (PMID 24889262, 2014). "Like FOXC1, FOXC2 plays a significant part in the evolution of different cancer types." (PMID 37626655, 2023).